MIR7855 (microRNA 7855)
Synonyms: hsa-mir-7855
Gene: MicroRNA gene on chromosome 14 (64,785,626 to 64,785,686, reverse strand). Ensembl gene ENSG00000284269.
Homologues: Orthologues: chimpanzee MIR7855 (100% identical).